CASP1 (caspase 1)
Diseases named in the same sentence as CASP1 in open-access papers (continued):
Sharing a sentence is not in itself a finding about the gene and the disease.
depression (74 papers, 2013 to 2026). "The expression and activation of caspase-1 in neurons is crucial for the process of neuroinflammation; indeed, chronic caspase-1 dysfunction can increase the risk of depression, PD, and AD." (PMID 40137863, 2025). "Several studies have reported that caspase 1, IL-1β, and IL-18 are associated with depression, anxiety, and fatigue, indicating the implication of the NLRP3 inflammasome in the pathophysiology of these diseases." (PMID 36675440, 2023). "Our previous study has also demonstrated that genetic deficiency of caspase-1 decreases chronic social defeat stress-induced depression- and anxiety-like behaviors via regulating the stability of surface AMPARs." (PMID 37369673, 2023). "Genetic deficiency of caspase-1 not only blocked CRS-induced depression-like behaviors, but also alleviated CRS-induced impairments in GABAergic neurotransmission." (PMID 37369673, 2023). "Caspase-1 have been shown to be associated with depression-like behavior in mice before and increased gene expression of its coding gene were observed in blood cells of untreated depressed patients." (PMID 31431611, 2019). "NLRP3-dependent caspase-1 activation was reported to be significantly implicated in the progression of systemic inflammation-induced depression triggered by LPS in mice depression model." (PMID 30233319, 2018). "Finally, reexpression of caspase-1 in the hippocampus of Caspase-1−/− mice increased susceptibility to stress-induced anxiety- and depression-like behaviors through inhibiting GAD67 expression and GABAARs-mediated synaptic transmission." (PMID 37369673, 2023). "This work illustrates that targeting the NLRP3/Casp-1/GSDMD–mediated pyroptosis may provide potential therapeutic benefits to stress-related astrocyte loss in the pathogenesis of depression." (PMID 34877938, 2021). "In addition, increases in the NLRP3 inflammasome and caspase-1 levels are associated with increases in serum IL-1B and IL-18 levels in patients with major depression." (PMID 34422020, 2021). "The emergence of depression is closely related to the stimulation of mature NLRP3 inflammasome triggering the activation of Caspase-1, which in turn promotes the maturation and release of pro-inflammatory cytokines." (PMID 40308754, 2025). "When NLRP3 is activated by stress, it regulates the activation of caspase-1, which in turn promotes the maturation of IL-1β in microglia, and the overproduction of cytokines in microglia contributes to the development of depression." (PMID 40308754, 2025). "Caspase-1 inhibition via genetic knockout or pharmacological intervention reduces depression and anxiety-like behaviors in mice." (PMID 41048915, 2025). "This, in turn, suppresses the activation of caspase-1 and decreases the production of IL-1β and IL-18, thereby improving mitochondrial energy metabolism and alleviating depression." (PMID 40699781, 2025). "Ferulic acid inhibited the activation of microglia and significantly decreased the contents of IL-1β, IL-6, and TNF-α in the prefrontal cortex of the CUMS-induced depression mouse model by inhibiting the NLRP3/caspase-1/NF-κB pathway." (PMID 38915473, 2024). "PSP demonstrated inhibitory effects on the upregulation of NLRP3, ASC, caspase-1, cleaved-caspase-1, and IL-1β in LPS-induced depression model in mice." (PMID 38389919, 2024). "Our study suggests that CRS dysregulates GABAergic neurotransmission via increasing the levels of caspase-1-mediated neuroinflammation in the hippocampus, ultimately leading to depression-like behaviors." (PMID 37369673, 2023). "Meanwhile, inhibition of caspase-1 levels through knockout gene or inhibitor can modulate the gut microbiota composition, thus alleviating depression-like behaviors." (PMID 37293210, 2023). "A recent study reveals that caspase-1 deletion prevents chronic mild stress-induced depression-like behaviors through improving the proptosis of astrocytes in the hippocampus." (PMID 37369673, 2023).
depression (continued). "Further studies also need to investigate the role of hippocampal caspase-1 in chronic stress-induced depression by using conditional caspase-1 knockout mice." (PMID 37369673, 2023). "Reexpression of caspase-1 in the hippocampus of Caspase-1−/− mice was sufficient to induce anxiety- and depression-like behaviors." (PMID 37369673, 2023). "In a rat model of depression induced by monosodium glutamate, it was found that both minocycline and VX-765 (a caspase-1-specific inhibitor) improve the depressive-like performance of rats." (PMID 35722622, 2022). "LPS-induced and chronic social defeat stress (CSDS) depression models have also reported the link with elevated caspase-1 and GSDMD." (PMID 36615696, 2022). "Recent research has revealed that the CASP1-mediated signaling pathway links environmental stress to depression-like behaviors by controlling the membrane integrity of glutamate receptors." (PMID 36353576, 2022). "NLR3P inflammasome cleavage of pro-caspase 1 into caspase 1 results in the production of IL1-β from these activated microglia in situations of neuroinflammation such as in depression." (PMID 35782423, 2022). "The NLRP3/ASC/caspase-1 system plays a key role in neuroinflammation in depression, and inhibition of the NLRP3/ASC/caspase-1 system reduces the expression of proinflammatory cytokines and inhibits activation of microglia." (PMID 35498131, 2022). "Our results showed that the expression levels of TLR4, MyD88, NF-κB-p65, TAK1, IRAK1, TRAF6, inflammasome-related NLRP3, ASC, and caspase-1 were all increased in rats of the depression model group." (PMID 33505499, 2021). "Genetic KO of GSDMD, Casp-1, and astrocytic NOD-like receptor protein 3 (NLRP3) inflammasome in mice alleviated depression-like behaviors and inhibited the pyroptosis-associated protein expression." (PMID 34877938, 2021). "The caspase 1 inhibitor Ac-YVAD-CMK can inhibit the activation of NLRP3 and the inflammation induced by LPS, indicating that NLRP3 inflammasome and caspase 1 are involved in the depression model induced by LPS." (PMID 34526897, 2021). "Procaspase-1 is subsequently converted to activated caspase-1, which further promotes the secretion of IL-1β, thereby generating a corresponding inflammatory response and promoting the pathogenesis of depression." (PMID 33505499, 2021). "The astrocytic NLRP3 KO results reported here suggest that astrocytic NLRP3 inflammasome had a significant effect on the astrocytic pyroptosis via the downstream Casp-1/GSDMD pathway in the pathophysiology of depression." (PMID 34877938, 2021). "Despite no changes in markers of oxidative stress, both in WKY rats, but mainly in the model of coexistence of depression and hypothyroidism, a strong increase of caspase-1 protein level was observed." (PMID 33562494, 2021). "In agreement with our data, overproduction of Caspase-1 in the hippocampus or intracerebroventricular administration of IL-1β induces depression- and anxiety-like behaviors in mice." (PMID 34258564, 2021). "In a case–control study, 20 patients with major depressive disorder exhibited high anxiety score and increased levels of caspase-1 and NLRP3 expression in peripheral blood mononuclear cells than did the healthy group." (PMID 31263417, 2019). "The NLRP3 inflammasome, involved in CASP1 activation, exerts a crucial effect on depression." (PMID 41503678, 2026). "Additionally, CRS can dysregulate GABAergic neurotransmission in the hippocampus by enhancing caspase 1-mediated neuroinflammation, which ultimately contributes to the emergence of depression-like behaviors." (PMID 40001487, 2025). "Furthermore, NLRP3/caspase-1/GSDMD pathway-mediated pyroptosis can cause psychiatric disorders, such as depression, complicating AA treatment." (PMID 39319843, 2025). "In addition, the expression levels of TLR4, P65, P-P65, NLRP3, ASC, caspase-1, and IL-1β were elevated in depression models." (PMID 38261756, 2024).
depression (continued). "Furthermore, mangiferin downregulates the contents of IL-18, IL-1β, IL-6, and TNF-α in the hippocampus of the CUMS-induced depression mouse model by inhibiting the NLRP3/ASC/caspase-1 pathway." (PMID 38915473, 2024). "Therefore, we use a variety of behavioral tests, stereotactic injection, electrophysiological recordings, immunofluorescence, and molecular experiments to determine the effects of caspase-1 on CRS-induced depression-like behaviors and GABAergic dysfunction." (PMID 37369673, 2023). "In agreement with the key role of caspase-1 in the MDD, in our study, CRS significantly increased the expression of caspase-1-IL-1β in the serum and hippocampus, and genetic deficiency of caspase-1 prevented CRS-induced depression-like behaviors via inhibiting the expression of IL-1β." (PMID 37369673, 2023). "To confirm the role of caspase-1 in the CRS-induced GABAergic dysfunction, we tested if enhanced caspase-1 expression in the hippocampus of Caspase-1−/− mice could induce depression-like behaviors and GABAergic dysfunction." (PMID 37369673, 2023). "Furthermore, pharmacological inhibition of caspase-1 prevents chronic restraint stress (CRS)-induced depression-like behaviors via regulating the gut microbiota composition." (PMID 37369673, 2023). "Three different NLRP3 inflammasome genes (NLRP3, ASC, and Caspase-1) were found to be substantially upregulated at the mRNA level following LPS treatment relative to baseline, consistent with a central role for this pathway in LPS-induced depression." (PMID 35113011, 2022). "Furthermore, when caspase-1 was specifically inhibited, this led to a decrease in depression-like behaviors triggered by multiple stimuli, such as estrogen deficiency, chronic mild stress, and LPS injection." (PMID 36339940, 2022). "This suggests that the increase in the protein expression of NLRP3, caspase-1, and IL-1β may have participated in anxiety-like and depression-like behavioral phenotypes in mice with atopic dermatitis." (PMID 36267291, 2022). "This suggests that NLRP3, caspase-1, and IL-1β may be involved in the anxiety-like and depression-like behavioral phenotypes of AD mice." (PMID 36267291, 2022). "Given the astrocytic loss in depression and the correlation between pyroptosis and nervous system diseases, it is tempting to speculate that the NLRP3/Casp-1/GSDMD–dependent pyroptotic process contributes to the astrocytic loss in the context of depression." (PMID 34877938, 2021). "We aimed to determine whether genetic deletion of Casp1, Nos2 and Ifngr affects depression- and anxiety-like behaviours in mice, either in the absence of stress or in response to CUS." (PMID 31015500, 2019). "NLRP3- and caspase-1-deficient mice are resilient to depressive-like behavior, indicating that inflammation caused by activation of the NLRP3 inflammasome regulates susceptibility to depression-like behaviors." (PMID 30174579, 2018). "Therefore, the reduction of depression by the B vitamins may be due to their inhibition of apoptosis, oxidative damage, neuroinflammation, and caspase-1-mediated inflammasome activation." (PMID 39968398, 2025). "The activation of NLRP3 inflammasome promotes the secretion of Caspase-1, which secretes downstream cytokines, NF-κB, TNFα, and other pro-inflammatory cytokines, and then induces apoptosis, which NLRP3 cascade has been implicated CNS disorders such as depression." (PMID 40308754, 2025). "We tended to speculate that the associations between CASP1, PCOS, and depression were reasonable." (PMID 38674428, 2024). "However, the exact role and precise mechanisms of caspase-1 in CRS-induced depression-like behaviors remains largely unknown." (PMID 37369673, 2023). "Additionally, reports proved that the activation of the Casp-1/IL-β signaling pathway could induce anxiety- and depression-like behaviors of mice." (PMID 34877938, 2021).
depression (continued). "It is understood that the maturation of IL-1β, which involves the cleavage of Caspase-1, relies on the NLRP3 inflammasome and significantly impacts depression." (PMID 40308754, 2025). "Fecal microbiota transplantation (FMT) from healthy mice to postpartum MDD (PPD) mice alleviated depression/anxiety-like behaviors, reduced NLRP3/caspase-1-mediated inflammation in the gut and hippocampus, increased SCFA levels." (PMID 41048915, 2025). "Further research is needed to explore the relationship between CASP1 and the comorbidity of PCOS and depression." (PMID 38674428, 2024). "There were five overlapping hub genes in the two datasets including CASP1, IRS2, PRKAR1A, SNAP23, and VTI1A, which were identified as the key genes in the comorbidity of PCOS and depression." (PMID 38674428, 2024). "In this study, we demonstrated that the levels of caspase-1-IL-1β pathway were increased in CRS mice and negatively correlated with depression-like behaviors." (PMID 37369673, 2023). "The therapeutic effect of PAP on depression-like behaviors and its regulatory role on protein expressions of NF-κB, NLRP3, ASC, Caspase-1, GSDMD-N, Cleaved-IL-1β, and Cleaved-IL-18, etc., paved the way for us to understand PAP and its effect on pyroptosis." (PMID 35401226, 2022). "A previous report showed that caspase-1, NLRP3 mRNA expression, and NLRP3 protein levels are increased in mononuclear blood cells in patients with depression." (PMID 35496273, 2022). "It proved that AFR has therapeutic effects on depression by verifying the BDNF-MEK signalling pathway and NLRP3/caspase-1 inflammatory signalling pathway in vitro and in vivo." (PMID 35938494, 2022). "It has recently been reported that patients with major depressive disorder have higher levels of NLRP3, caspase-1, and IL-1β in serum or peripheral blood mononuclear cells." (PMID 36339940, 2022). "In CUMS-induced rat model of depression, icariin produces anti-neuroinflammatory and anti-depression effect partially by the inhibition of NF-ĸB pathway and the NLRP3-inflammasome/caspase-1/IL-1β axis." (PMID 35165207, 2022). "NLRP3, caspase-1, ASC, IL-6, and IL-1β in this signaling pathway are closely related to inflammation and depression." (PMID 36556951, 2022). "Research showed that in the LPS-induced depression murine model, following LPS treatment for 24 h, NLRP3 brain inflammation, ASC and caspase 1 and IL-1β mRNA protein levels increased significantly." (PMID 34526897, 2021). "Treatment of db/db mice with NLRP3 inflammasome inhibitor MCC950 ameliorated anxiety- and depression-like behaviors as well as cognitive dysfunction, and reversed increased NLRP3, ASC, and IL-1βexpression levels and caspase-1 activity in hippocampus." (PMID 29495433, 2018). "Studies have found that activation of the NLRP3/caspase-1/Gasdermin D (GSDMD) pathway leads to pyroptosis of astrocytes in the hippocampus of chronically stressed mice, enhancing neuroinflammatory responses and mediating the onset of depression." (PMID 40699781, 2025). "Mitochondrial transplantation may, therefore, exert its therapeutic effects on CRS-induced depression by restoring mitochondrial function and suppressing the NLRP3/caspase 1/IL1β signaling pathway." (PMID 40001487, 2025). "Studies have found that NLRP3 activation is essential to depression and fatigue pathogenesis, and NLRP3/caspase-1 inhibition therapy may be a promising option for treatment." (PMID 39339809, 2024). "In the present study, we hypothesized that CRS upregulated the levels of caspase-1, subsequently impaired GABAARs neurotransmission via reducing the GAD67 expression, eventually resulting in depression-like behaviors." (PMID 37369673, 2023). "In this study, we found that serum and hippocampal caspase-1-IL-1β levels increased significantly in chronic restraint stress (CRS) mice, and a significant negative correlation occurred between levels of caspase-1 and depression-like behaviors." (PMID 37369673, 2023).
depression (continued). "It was shown that dimethyl fumarate can reduce IL-1β, IL-18, caspase-1, and NLRP3 levels through the Nrf2/NF-κB signaling pathway, thus inhibiting LPS-induced microglial pyroptosis and disease manifestations in LPS-challenged depression mice." (PMID 35722622, 2022). "Our data showed that stress stimuli significantly increased the protein expression of NLRP1, ASC, and caspase-1, and also markedly increased the mRNA levels of NLRP1, ASC, and caspase-1, indicating NLRP1 inflammasome was activated in stress-induced depression models." (PMID 32513185, 2020). "The mRNA expression levels of NLRP3, CASP1, and IL1B were higher in liver biopsies from AIH patients with depression than in those without depression." (PMID 41503678, 2026). "However, the result of the SNP genetic analysis did not support CASP1 as a key gene for the comorbidity of PCOS and depression." (PMID 38674428, 2024).